MIF (macrophage migration inhibitory factor)
Diseases named in the same sentence as MIF in open-access papers (continued):
Sharing a sentence is not in itself a finding about the gene and the disease.
infection (continued). "It has been shown that DENV2 infection triggers MIF expression and secretion, which enhances DENV2 replication in HuH-7 cells." (PMID 32545679, 2020). "Among these cytokines, MIF is the only cytokine that is preformed inside cells and can be secreted very early during infection." (PMID 32545679, 2020). "Recently, it was regarded as a multi-functional protein, positioning MIF as a mediator during the inflammatory response to combat infection and in immunoinflammatory and autoimmune diseases." (PMID 32753724, 2020). "MIF, a macrophage migration inhibitory factor, which is necessary for leukocytes to transport to infection site." (PMID 32676073, 2020). "In the wild-type animals, infection provokes a sharp increase in cell numbers within the MLNs, which is diminished in the MIF−/− mice." (PMID 31708913, 2019). "Homologs of MIF have been discovered in many parasitic species infecting mammalian hosts and it has been suggested that parasites express MIF to manipulate the host immune response during infection." (PMID 31105655, 2019). "MIF, a proinflammatory cytokine that has been described as a major factor during infection and septic shock, was demonstrated to have a role in BBB damage, as evidenced by the induction of a significant decrease in ZO-1 and occludin, as well as inflammation." (PMID 31671896, 2019). "MLN cell populations were analyzed by flow cytometry at 14 and 28 days post-infection, and similar increases in Foxp3+ Treg numbers were seen in both wild-type and MIF−/− mice infected with H. polygyrus." (PMID 31708913, 2019). "In the oral cavity, the constitutive expression of MIF is crucial, since MIF can regulate the response of the host against to infections and stress." (PMID 30868074, 2019). "Another study evaluated the effect of MIF in human placental explants infected with T. gondii, demonstrating that controlling the infection depends on gestational age." (PMID 31068920, 2019). "Recent research in parasite MIF has provided a mechanism by which parasites evade the immune response by interfering with the development of immunological memory during infection, allowing them to re-infect their host." (PMID 31497025, 2019). "Further analysis indicated that MIF was required for the induction of inflammation in response to vvIBDV infection." (PMID 31632367, 2019). "MIF promotes the migration and recruitment of leukocytes in the sites of infection and inflammation and it is rapidly released in response to stimuli like microbial products, proliferative signals, and hypoxia." (PMID 30868074, 2019). "Compared with the control level, MIF expression was increased 2.25-fold (MOI = 100) by P. gingivalis ATCC 33277 infection for 24 h (P < 0.01)." (PMID 29482504, 2018). "Our results demonstrated that MIF-/- mice have more accentuated change in body weight and succumbed to infection first than their WT counterparts." (PMID 29867817, 2018). "Studies have demonstrated that MIF can inhibit the migration and promote the aggregation of macrophages at sites of local inflammation or infection." (PMID 29773680, 2018). "The effect was highest as early as 4 days post-infection when using the 25 ng/ml MIF-stimulated MDMs while it occurred at day 7 post-infection for the 1 ng/ml MIF condition." (PMID 29997630, 2018). "Migration inhibitory factor (MIF) is a pro-inflammatory cytokine that plays important roles in physiology, pathology, immunology and parasitology, including the control of infection by protozoa parasites such as Toxoplasma gondii." (PMID 29867817, 2018). "Our results demonstrated that an increase in MIF expression due to infection was followed by a decrease in CD74 expression in the uterus from both non-pregnant and pregnant WT females." (PMID 29867817, 2018). "Results from these analyses indicated that GAS induces a 2-fold or greater increase in GM-CSF, IL-1β, IL-6, and MIF in WT vs. mock infection." (PMID 30018884, 2018).
infection (continued). "In line with the previous reports, our results indicated that the MIF plasma level during the acute HIV infection (<6-month post-infection) was 30-fold higher when compared to uninfected individuals." (PMID 29997630, 2018). "During HIV infection, increased MIF plasma levels have been observed during the acute phase of infection and remained elevated." (PMID 29997630, 2018). "In conclusion, MIF has been shown to be an important factor that is expressed at the maternal–fetal interface in response to T. gondii infection, controlling infection but inducing abortion and pathology." (PMID 29867817, 2018). "The ELISA results revealed that P. gingivalis ATCC 33277 infection significantly increased MIF secretion in EA.hy926 cells." (PMID 29482504, 2018). "We found that pregnant MIF-/- females succumbed to infection before their WT counterparts (P = 0.0095)." (PMID 29867817, 2018). "The intracellular protein level of MIF was significantly reduced in ECs infected with adenovirus-KLF2 compared to the one with adenovirus-GFP infection by Western blotting." (PMID 29403061, 2018). "In the present study, cytokine production at the maternal–fetal interface reflects the systemic levels, showing an important and similar Th1-type profile in response to infection in both WT and MIF-/- groups." (PMID 29867817, 2018). "In summary, our study revealed that the MIF induced by P. gingivalis ATCC 33277 infection not only promoted ICAM-1 expression inendothelial cells but also activated monocyte-endothelial cell adhesion." (PMID 29482504, 2018). "MIF is a proinflammatory cytokine, which has been highlighted as a key player in infection and septic shock." (PMID 30340642, 2018). "Only GJ18 experienced any systemic pro-inflammatory response with transiently increased plasma concentrations of IL-12, CXCL8, and MIF by day 1 to 2 post-infection that rapidly resolved to baseline and later increases in CCL2 and CCL11." (PMID 29259582, 2017). "Interleukin-6 (IL-6), interleukin-8 (IL-8) and macrophage migration inhibitory factor (MIF) were produced during Huh-7 DENV infection at significant levels in cell supernatants starting from 48 h after infection." (PMID 28591408, 2017). "Although MIF mRNA levels were increased from 6 h after infection with T. gondii, the increased expression levels of MIF mRNA were reduced significantly in Nox4−/− macrophages." (PMID 28743960, 2017). "In the recent year, many researchers paid attention on the possible role of MIF gene in the innate immune system, pathogenesis of infection and inflammation." (PMID 29208960, 2017). "The results showed that T. gondii-mediated protein and mRNA MIF levels were induced initially, from 6 h after infection, and increased continually until 48 h in BMDMs." (PMID 28743960, 2017). "UGB inhibited significantly MIF and IL-8 levels from 48 to 72 h after infection and UGL inhibited IL-6 (72 h) and IL-8 (48-72 h)." (PMID 28591408, 2017). "The direct assessment of the BBB function and MIF expression in the peripheral phase of TBEV infection would be necessary to clarify this issue but is difficult to perform in human infection in a clinical setting." (PMID 28646884, 2017). "MIF plays a role in resistance to infection with Trypanosoma cruzi, T. gondii and Leishmania major but many studies have also reported its contribution in disease pathology." (PMID 29228011, 2017). "All of these results indicated that MIF of H. contortus were excretory/secretory antigens and interacted with the host immune system during infection." (PMID 28402951, 2017). "We observed that, upon i.p. infection with T. gondii, newly recruited monocytes (Ly6Chigh and Ly6Clow) populated the peritoneal cavity of infected mice in a MIF-independent manner." (PMID 27057101, 2016). "Our data demonstrate a novel role for MIF promoting the resistance to T. gondii-infection by inducing classical activation of inflammatory monocytes Ly6Chigh and their conversion into TipDCs." (PMID 27057101, 2016).
infection (continued). "The data suggest that MIF induces IFN-γ-producing NK cells during the acute infection with T. gondii." (PMID 27057101, 2016). "These factors include OSM, IL-4 (gene up-regulated on day 1 post infection) and MIF (macrophage migration inhibitory factor) that induces P- and E-selectin and vascular cell adhesion molecule 1 (VCAM-1)." (PMID 25719526, 2015). "Among these cytokines, macrophage migration inhibitory factor (MIF) has been highlighted as a key player in septic shock and infection." (PMID 25617421, 2015). "Another central cytokine is the macrophage migration inhibitory factor (MIF), which was released following infection with the digenean trematode parasite Schistosoma mansoni." (PMID 25295041, 2014). "When first described, MIF was shown to inhibit macrophage mobilization to maintain these cells at a site of injury or infection." (PMID 24887129, 2014). "Among the chemokines (MCP-1, MIF and GROα), only GROα synthesis was significant at 24 h post infection and the parasite burden decreased between 8 h and 24 h post infection (NS)." (PMID 24886982, 2014). "As in Mif−/− mice, the pro-inflammatory cytokine production was decreased and IL-10 production was elevated during the chronic stage of infection upon anti-MIF IgG treatment of WT mice." (PMID 25255103, 2014). "We also explored the effects of DV infection on the production of MIF in human blood mononuclear cells (THP-1) and human umbilical cord vein endothelial cells (HUVECs)." (PMID 23383040, 2013). "Using a murine model of CCC, we found that MIF protein expression was strongly upregulated in the myocardial inflammatory lesions at a time of infection (120 days p.i.)when heart parasitism and marked leukocyte infiltration are both present." (PMID 23451183, 2013). "Preformed MIF protein is found in many cell types and is released in response to different stimuli, such as infections and cytokine stimulation." (PMID 22496958, 2012). "Second, it is possible that the transcription level of the MIF gene is easily influenced by MDV during the early stages of the infection." (PMID 23116199, 2012). "MIF has been reported to be an injury marker in kidney inflammatory disease, and consistently, our results revealed the utility of urinary MIF in determined AKI under infection." (PMID 23319831, 2012). "A series of studies demonstrated a putative role of MIF on placental biology upon infection with T. gondii." (PMID 22496958, 2012). "MIF is released from an intracellular pool in response to pathological stimuli including infection and inflammatory activation." (PMID 23319831, 2012). "Since it is well documented that human epithelial cells participate in neutrophil recruitment in response to infection, we determined if MIF affects IL-8 synthesis by corneal epithelial cells." (PMID 20361053, 2010). "At 48 h after infection the differences between the MIF KO and C57Bl6 mice increased dramatically: there were about 100-fold fewer bacteria recovered from the corneal cell exterior in the infected MIF KO mice compared to the C57Bl6 controls." (PMID 20361053, 2010). "MIF is one of cytokine known to be upregulated by glucocorticoids (GCs), which suggests MIF plays a key role in regulating host global responses to infections, as GCs are released from the hypothalamus-pituitary-adrenal axis." (PMID 22046508, 2010). "We have identified and characterized the involvement of a snail homologue of the cytokine MIF (Macrophage Migration Inhibitory Factor) in the snail immune responses to infection by the parasite." (PMID 20886098, 2010). "Treatment of mice with recombinant MIF at the time of infection resulted in increased MIF concentrations in lung homogenates 48 hours later (from 33±1.3 to 729±56.6 ng/ml; P<0.001)." (PMID 20169062, 2010). "The improved outcomes in MIF KO mice was also obtained with P. aeruginosa strain PAO1 48 h following infection." (PMID 20361053, 2010).
infection (continued). "As P. aeruginosa bacteria found in the cornea during infection are mostly intracellular, we determined if MIF modulated the uptake of bacteria by corneal epithelial cells using in vitro invasion assays." (PMID 20361053, 2010). "We find that treatment of the infected mice with small molecule inhibitor of MIF activity after the onset of the infection promoted recovery from disease." (PMID 20361053, 2010). "The contribution of MIF during responses to infections by a variety of pathogens, including bacteria, viruses, and parasites is currently an area of active research." (PMID 20361053, 2010). "One μg of rMIF administered topically onto the eye of infected MIF KO mice restored the wild-type response to infection with P. aeruginosa strain 6294." (PMID 20361053, 2010). "Anti-MIF treated mice showed lower bacterial loads in their lungs upon infection with a low inoculum." (PMID 20169062, 2010). "With this low inoculum, none of the mice showed positive Burkholderia cultures in liver or blood, suggesting that anti-MIF treatment inhibits the growth of B. pseudomallei in the lungs after infection with a relatively low bacterial dose." (PMID 20169062, 2010). "MIF protein is present in most cells including pituitary cells, T cells, macrophages/monocytes, and is released in response to infection and stress." (PMID 19413900, 2009). "During infection, the pro-inflammatory cytokine macrophage migration inhibitory factor (MIF) released by liver, immune, and endothelial cells has been shown to promote shock by inducing autophagy-driven degradation of vascular endothelial cells, resulting in vascular leakage." (PMID 41305369, 2025). "This might explain the chemokine-like properties of MIF, thus facilitating the migration and recruitment of leukocytes to sites of infection and inflammation." (PMID 41159021, 2025). "MIF secretion is also induced by glucocorticoids in pro-inflammatory states such as infection or sepsis and follows a bell-shaped dose–response curve, with secretion being inhibited at very high glucocorticoid levels to protect the host from a potentially life-threatening inflammatory response." (PMID 38732068, 2024). "Interestingly, Tb927.6.4140-KO parasites induced higher MIF levels, corroborating the notion of a stronger peritoneal inflammation at very early stages of infection." (PMID 38413606, 2024). "Additionally, OnCL-K1 exhibits the ability to modulate the levels of inflammatory factors, such as IL-6 and IL-10, as well as chemotactic migration factors, including IL-8 and MIF, in Nile tilapia post-infection with S. agalactiae." (PMID 38473757, 2024). "Furthermore, the study examined the levels of IL-6, IL-10, IL-8, and MIF gene expression in different tissues and organs following artificial infection of tilapia, as well as the extent of tissue damage." (PMID 38473757, 2024). "Overall, a comprehensive understanding of the role of MIF and D-DT in infections could lead to new strategies for the diagnosis, treatment, and management of infectious diseases." (PMID 38275363, 2023). "Moreover, MIF levels were higher in severe patients than in moderate patients, suggesting MIF as a potential indicator of disease prognosis in early infection stages." (PMID 37568438, 2023). "Conversely, the deleterious effects of MIF in other infections may be due to its potential to exacerbate inflammation and contribute to tissue damage." (PMID 38275363, 2023). "Compared to MIF, less is known about the functioning of D-DT, and further research is needed to elucidate its role in the immune system and explore its potential as a therapeutic target in various infections." (PMID 38275363, 2023). "Conversely, in other infections, MIF could contribute to deleterious effects, potentially promoting chronic inflammation and tissue damage." (PMID 38275363, 2023).
infection (continued). "However, in the presence of infection, untreated and 32 μg/mL oleoresin-treated cells upregulated or downmodulated MIF in comparison to medium (#P < 0.05) or medium Tg (***P < 0.0001), respectively." (PMID 36860986, 2023). "MSCs derived from human BM and salivary gland stimulated by LPS boost the anti-microbial functions of neutrophils by releasing high levels of macrophage migration inhibitory factor (MIF) and inflammatory cytokines (IL-6 and IL-8) and eliminating the infection and inflammation." (PMID 37058201, 2023). "One factor that could also influence in which infections MIF exerts a protective or deleterious effect is the affected organ, as MIF could also exert organ-specific protective effects in diseases." (PMID 38275363, 2023). "Immunohistochemistry of the spleens from LdWT, and LdMIF−/− 9 days post infection showed the presence of TUNEL+ cells in LdWT but much less in LdMIF−/− infection indicating that deletion of MIF promotes the survival of T cells in the infected spleens consistent with our flow cytometric analysis." (PMID 37147351, 2023). "Greater numbers of larger cells were evident in wild-type mice following infection, but no expansion was observed in the MIF-deficient hosts." (PMID 35288645, 2022). "For example, purified recombinant MIF was found to activate murine macrophages to kill L. major parasites, with maximal effects at concentrations corresponding to levels found in vivo during infection." (PMID 35464430, 2022). "MIF-deficient mice show defective innate responses following infection, lacking intestinal epithelial tuft cell hyperplasia or upregulation of goblet cell RELMβ, and fail to expand eosinophil, type 2 innate lymphoid cell (ILC2) and macrophage (M2) populations." (PMID 35288645, 2022). "Other studies have shown that low MIF production increases the severity of the infection." (PMID 36093199, 2022). "Together these findings may suggest that a triad MIF/GC/IL-10 can be operative during infections in the regulation of inflammation." (PMID 35464430, 2022). "The phenotype and infection rate of CD4TLs from PWH were analyzed after MIF stimulus." (PMID 36298774, 2022). "Accordingly, during infections a balanced equilibrium between MIF (pathogen control) and IL-10 (pathology control) may confer tolerance towards an infectious disease." (PMID 35464430, 2022). "We also assessed ILC2 responses in MLNs from naive and infected mice, defined as lineage-negative (Lin−) CD45+ICOS+GATA3+ cells; both the percentages and total numbers were greatly reduced in MIF-deficient mice, with no increase apparent following infection." (PMID 35288645, 2022). "Moreover, CD74 is an indispensable part of the receptor complex of macrophage migration inhibitory factor (MIF), and macrophages can produce IL-8 that chemotactic leukocytes to the site of infection." (PMID 36405762, 2022). "Alveolar macrophages and the immune cells in mucosa-associated lymphoid tissue (MALT) could be responsible for the elevated MIF expression during infection." (PMID 35237527, 2021). "Upon infection, the expression of MIF was significantly increased in the spleen, lung, and heart." (PMID 35237527, 2021). "High MIF levels might indicate an excessive response in the case of pathological inflammation/infection, which could be harmful to the health of the pregnancy and fetus." (PMID 33673075, 2021). "Besides, we found that the expression of MIF was dramatically increased in all lymphoid organs in response to the duration of infection." (PMID 35237527, 2021). "MIF is an acute-phase secretory protein that appears in the blood at 2–8 h of infection." (PMID 35237527, 2021). "MIF response can become exaggerated in many infections, inflammatory, and autoimmune diseases." (PMID 33673075, 2021). "The pro-inflammatory activity of MIF has been shown to be protective against Leishmania major infection in mouse models of cutaneous disease, however the precise role of this cytokine in human infections is less clear." (PMID 32244916, 2020).